ZNRF4 (zinc and ring finger 4)
Description:
E3 ubiquitin-protein ligase that acts as a negative regulator of NOD2 signaling by mediating ubiquitination and degradation of RIPK2. Also catalyzes ubiquitination and proteasomal degradation of CANX within the endoplasmic reticulum. Could have a role in spermatogenesis (By similarity).
Synonyms: RNF204; spzn; Ssrzf1; SPERIZIN
Tractability: Antibody: UniProt predicts a signal peptide or a membrane-spanning region.
Gene: Protein-coding gene on chromosome 19 (5,455,417 to 5,456,856, forward strand). Ensembl gene ENSG00000105428.
Subcellular location: Endoplasmic reticulum membrane
Gene Ontology:
Molecular function: protein binding; ubiquitin protein ligase activity
Biological process: negative regulation of nucleotide-binding oligomerization domain containing 2 signaling pathway; proteasome-mediated ubiquitin-dependent protein catabolic process; ubiquitin-dependent protein catabolic process; negative regulation of cell cycle; negative regulation of intracellular signal transduction; protein ubiquitination
Cellular component: endoplasmic reticulum; endoplasmic reticulum membrane; cytoplasm; endomembrane system
Genetic constraint (gnomAD): Loss-of-function variants: 0 observed, 0.31 expected, observed/expected ratio (o/e) 0, 90% interval 0 to 1.86. That is too few expected variants to judge how well the gene tolerates losing a copy. Missense variants: 569 observed, 584.56 expected, observed/expected ratio (o/e) 0.97, 90% interval 0.91 to 1.04. Synonymous variants: 291 observed, 269.07 expected, observed/expected ratio (o/e) 1.08, 90% interval 0.98 to 1.19.
Homologues: Orthologues: macaque ZNRF4 (91% identical), pig ZNRF4 (62% identical), mouse Znrf4 (40% identical), rat Znrf4 (39% identical), zebrafish rnf167 (28% identical), tropical clawed frog rnf167 (26% identical). Paralogues in human: RNF13 (30% identical), RNF167 (30% identical), RNF130 (16% identical), RNF149 (16% identical), RNF150 (15% identical), RNF128 (14% identical), RNF133 (14% identical), RNF148 (14% identical), RNF215 (10% identical).
Diseases named in the same sentence as ZNRF4 in open-access papers:
ZNRF4 is named in the same sentence as 4 diseases in open-access papers, as found by Europe PMC text mining. Sharing a sentence is not in itself a finding about the gene and the disease. The quoted sentences say what the papers report.
breast carcinoma (1 paper, 2015). "Aberrant protein degradation may be important in this cancer, as three of the 14 mutated genes (USP4, USP31, and ZNRF4) in the breast cancer are involved in the ubiquitin–proteasome pathway." (PMID 26432421, 2015).
Listeria monocytogenes infection (1 paper, 2017). "We also observed that MDP stimulation and Listeria monocytogenes infection upregulated ZNRF4 at the protein level in human primary monocytes." (PMID 28656966, 2017). "Znrf4 knockdown monocytes have sustained nuclear factor kappa-light-chain-enhancer of activated B cells (NF-κB) activation, and Znrf4 knockdown mice have reduced NOD2-induced tolerance and more effective control of Listeria monocytogenes infection." (PMID 28656966, 2017).
bacterial infection (1 paper, 2017). "We next examined the physiological relevance of ZNRF4-mediated RIP2 regulation during NOD2-tolerant conditions in the context of bacterial infection." (PMID 28656966, 2017). "However, NOD2-tolerized Znrf4 knockdown macrophages showed significantly enhanced ability to control bacterial infection." (PMID 28656966, 2017).
ZNRF4 also shares sentences with these, for which no sentence is quoted: cancer (1 paper).